HSBP1 (heat shock factor binding protein 1)
Description:
Negative regulator of the heat shock response. Negatively affects HSF1 DNA-binding activity. May have a role in the suppression of the activation of the stress response during the aging process.
Synonyms: NPC-A-13
Tractability: PROTAC: ubiquitination databases record sites on it; its protein half-life has been measured.
Gene: Protein-coding gene on chromosome 16 (83,719,311 to 83,819,737, forward strand). Ensembl gene ENSG00000230989.
Subcellular location: Nucleus
Subcellular location (Human Protein Atlas): Nuclear speckles; Plasma membrane; Golgi apparatus
Pathways (Reactome):
Cellular responses to stimuli: Attenuation phase; HSF1 activation; HSF1-dependent transactivation
Gene Ontology:
Molecular function: identical protein binding; protein binding; transcription corepressor activity
Biological process: axonal transport of mitochondrion; negative regulation of transcription by RNA polymerase II; muscle contraction
Cellular component: nuclear speck; nucleoplasm; nucleus; axon cytoplasm
Genetic constraint (gnomAD): Loss-of-function variants: 3 observed, 4.85 expected, observed/expected ratio (o/e) 0.62, 90% interval 0.28 to 1.53. That is too few expected variants to judge how well the gene tolerates losing a copy. Missense variants: 101 observed, 71.29 expected, observed/expected ratio (o/e) 1.42, 90% interval 1.21 to 1.67. Synonymous variants: 38 observed, 24.27 expected, observed/expected ratio (o/e) 1.57, 90% interval 1.2 to 1.92.
Homologues: Orthologues: chimpanzee HSBP1 (100% identical), macaque HSBP1 (99% identical), dog HSBP1 (97% identical), guinea pig HSBP1 (97% identical), pig HSBP1 (97% identical), rabbit HSBP1 (93% identical), mouse Hsbp1 (88% identical), rat Hsbp1 (88% identical), zebrafish hsbp1b (84% identical), tropical clawed frog hsbp1 (83% identical), zebrafish hsbp1a (79% identical), Drosophila melanogaster CG5446 (61% identical), and 1 more. Paralogues in human: HSBP1L1 (30% identical).
Diseases named in the same sentence as HSBP1 in open-access papers:
HSBP1 is named in the same sentence as 15 diseases in open-access papers, as found by Europe PMC text mining. Sharing a sentence is not in itself a finding about the gene and the disease. The quoted sentences say what the papers report.
ovarian carcinoma (5 papers, 2020 to 2025). A malignant neoplasm originating from the surface ovarian epithelium. "Lin28A can enhance the mRNA stability and protein expression of HSBP1, which is significantly correlated with poor survival outcomes in ovarian cancer patients." (PMID 39150660, 2025). "In this study, we further confirmed that Lin28A can up-regulate the protein expression of RAN/HSBP1 to promote the stemness, the proliferation, the invasion and to inhibit the apoptosis of ovarian cancer cells." (PMID 32398961, 2020). "Then we detected the expression of Lin28A, RAN and HSBP1 in 47 ovarian benign tumor tissues and 96 ovarian malignant tumor tissues by immunohistochemical analysis." (PMID 32398961, 2020). "Moreover, RAN and HSBP1, when knocked down in ovarian cancer cells with high Lin28A expression, resulted in reduced malignancy characteristics, such as cell survival, invasion, and tumor growth in vivo, alongside increased apoptosis rates." (PMID 39150660, 2025). "Second, the role of Lin28A in regulating HSBP1 could be specific to ovarian cancer due to its involvement in maintaining stemness characteristics, which are more pronounced in ovarian cancer stem cells." (PMID 39150660, 2025). "First, the tissue-specific expression and regulatory mechanisms of HSBP1 may differ significantly between ovarian cancer and PRCC." (PMID 39150660, 2025). "Additionally, HSBP1 was reported to be overexpressed in ovarian cancer and may be regulated by corresponding lncRNAs." (PMID 39150660, 2025). "In ovarian cancer, Lin28A enriched the mRNA of RAN and HSBP1, which was negatively correlated with survival and prognosis." (PMID 34868981, 2021). "HSBP1 is a 76-amino-acid protein that binds to heat shock factor 1(HSF1), which can be enhanced through lin28A to regulate the stem-like characteristics of ovarian cancer." (PMID 36276091, 2022).
breast carcinoma (2 papers, 2008 to 2019). "Expression levels of the other two, dysbindin domain containing 1 (DBNDD1) and heat shock binding protein 1 (HSBP1) could be confirmed by RT-qPCR and may be the subject of future breast cancer research." (PMID 18416817, 2008).
oral squamous cell carcinoma (2 papers, 2021 to 2023). "FLI1 is shown to promote glioblastoma radioresistance by regulating HSBP1, and its expression is associated with radiation resistance in oral squamous cell carcinoma." (PMID 36814284, 2023).
autism (1 paper, 2022). Persistent deficits in social interaction and communication and interaction as well as a markedly restricted repertoire of activity and interest as well as repetitive patterns of behavior. "Finally, HSBP1 and IGF1R were found differentially expressed in autism and, directly or indirectly, modulated by microbiota; namely, HSBP1 is down-regulated after antibiotic administration, and IGF-1 level is affected by gut microbiota composition." (PMID 35405953, 2022).
melanoma (1 paper, 2016). A malignant, usually aggressive tumor composed of atypical, neoplastic melanocytes. "Regardless of how the reduction of HSBP1 is achieved, melanoma cells without HSBP1 show increased thermosensitivity." (PMID 27626679, 2016).
osteosarcoma (1 paper, 2022). A usually aggressive malignant bone-forming mesenchymal neoplasm, predominantly affecting adolescents and young adults. "An 85-amino-acid polypeptide with a calculated molecular weight of about 9.7 kDa and remarkable antiproliferative activity against MG-63 osteosarcoma cells was purified from antlion, and identified as a homolog of HSBP1." (PMID 37551169, 2022).
ovarian tumor (1 paper, 2020). "Meanwhile, the results of immunohistochemistry confirmed that shRAN or shHSBP1 caused the down-regulation of Vimentin, N-cadherin, and promoted the expression of E-cadherin, indicating that the knockdown of RAN and HSBP1 inhibited the invasive ability of ovarian tumor in vivo." (PMID 32398961, 2020).
tumor (10 papers, 2020 to 2025). "High expression of HSBP1 might also enhance the efficacy of ICIs by preventing tumor immune escape and increasing immune mutation burden." (PMID 39150660, 2025). "The majority of DEGs related to this pathway (ITGAV, KDR, VEGFB, AKT1, VEGFA) were downregulated in tumor cells except for HSBP1 and SHC2." (PMID 39245631, 2025). "It has been discovered that HSBP1 modulates the proliferation, differentiation and invasion of tumour cells, thereby substantially enhancing the tumour's invasive capacity." (PMID 39823159, 2025). "Substantial evidence supports that the molecular function of HSBP1 is involved in cell growth and tumour differentiation." (PMID 39823159, 2025). "In this case, HSBP1 is also overexpressed, suggesting that tumor cells manage to produce more WASH complexes through the up-regulation of the HSBP1 assembly factor." (PMID 33869225, 2021). "And after knocking down of RAN or HSBP1 in Lin28A highly expressed OC cells, the survival and invasion of OC cells and tumor size of OC xenograft in nude mice were markedly inhibited and apoptosis was increased." (PMID 32398961, 2020). "The images of IHC staining suggested that tumor tissues of shRAN (#1 and #2) and shHSBP1(#1 and #2) group had a lower expression levels of RNA and HSBP1 compared with the control group A2780 Lin28A shNC group." (PMID 32398961, 2020). "Notably, GCLC and HSBP1 appeared to play active roles in regulating the tumor microenvironment and immune responses in our study." (PMID 39150660, 2025). "HSBP1 can inhibit elastin-induced ferroptosis in tumor cells." (PMID 40128669, 2025). "Additionally, we evaluated variances in immune cell infiltration, tumor mutation burden, and TIDE scores between the high- and low-risk groups, along with the expression levels of GCLC and HSBP1." (PMID 39150660, 2025). "To examined the effect of RAN/HSBP1 on the tumor formation of OC cells, we transplanted A2780 Lin28A shNC, shRAN (#1 and #2) and shHSBP1 (#1 and #2) cells into the Balb/c nude mice to form tumor, separately." (PMID 32398961, 2020). "Nevertheless, in a conflicting result, HSBP1 knockdown revealed a significant association with adverse pathological characteristics of UBC cell lines although the authors have not observed any association with apoptosis effect, chemotherapeutic sensitivity, and clinical outcomes on tumor cells." (PMID 37501157, 2023). "The mRNA expression of KEAP1, HSBP1, SAT1, CISD1, and GPX4 were significantly different between tumor and the adjacent tissues." (PMID 34692692, 2021).
cancer (5 papers, 2015 to 2025). A tumor composed of atypical neoplastic, often pleomorphic cells that invade other tissues. "Additionally, aberrant expression of PCBP3 and HSBP1 were significantly associated with cancer development and therapy resistance." (PMID 34212178, 2021). "On the other hand, the increased candidates included proteins involved in the blockade of cancer cell migration and invasion (SCAI, CARMIL2), autophagy activation (HSBP1, RILP) as well as proteins that can be considered as anti-tumorigenic (SCG2, DIP2A, HSBP1)." (PMID 39833546, 2025).
infection (1 paper, 2021). The state of being infected such as from the introduction of a foreign agent such as serum, vaccine, antigenic substance or organism. "The anti-picornaviral function of the FIP200-ATG13 subcomplex was abolished when HSBP1 was depleted, inferring that this subcomplex negatively regulates HSBP1’s pro-picornaviral function during infections." (PMID 34869056, 2021). "Cell infection with these viruses also caused a relocalization of HSBP1 from the cytoplasm into the nucleus, i.e. more than 90% of infected cells displayed nuclear GFP-HSBP1, showing that HSBP1 redistribution is triggered by all the tested picornaviruses." (PMID 34869056, 2021). "Thus, we tested whether the relocalization of HSBP1 is specific to EMCV or also occurs upon infection with CVB3 and EV71." (PMID 34869056, 2021). "To this aim, we infected wild type, ATG7KO and ATG13KO cells after knocking down or not HSBP1, and then measured EMCV infection by IF." (PMID 34869056, 2021). "GFP-HSBP1 relocalization was strongly reduced when we inhibited virus replication by either treating cells with cycloheximide 1 h after exposure to EMCV or inoculating cells with inactivated EMCV, showing that HSBP1 redistribution is induced by an active EMCV infection (data not shown)." (PMID 34869056, 2021).
HSBP1 also shares sentences with these, for which no sentence is quoted: Alzheimer disease (1 paper); glioblastoma (1); keratitis (1); ovarian benign tumor (1); viral infection (1).